ENSG00000271810 (novel protein, PPM1J-RHOC readthrough)
Gene: Protein-coding gene on chromosome 1 (112,702,614 to 112,711,433, reverse strand). Ensembl gene ENSG00000271810.
Genetic constraint (gnomAD): Loss-of-function variants: 22 observed, 31.37 expected, observed/expected ratio (o/e) 0.7, 90% interval 0.5 to 1. Missense variants: 239 observed, 327.49 expected, observed/expected ratio (o/e) 0.73, 90% interval 0.66 to 0.81. Synonymous variants: 127 observed, 129.23 expected, observed/expected ratio (o/e) 0.98, 90% interval 0.85 to 1.14.